REL (REL proto-oncogene, NF-kB subunit)
Diseases named in the same sentence as REL in open-access papers (continued):
Sharing a sentence is not in itself a finding about the gene and the disease.
viral infection (10 papers, 2009 to 2024). "Phosphorylated STATs dimerize and form a complex called the ISGF3 transcription factor that ultimately activates IFN-stimulated genes against viral infections, preventing the activity of dimeric NF-kB/REL complexes by trapping REL dimers in the cell cytoplasm." (PMID 37376674, 2023).
autoimmune disease (9 papers, 2009 to 2025). A disorder resulting from loss of function or tissue destruction of an organ or multiple organs, arising from humoral or cellular immune responses of the individual to their own tissue constituents. "Based on the important roles that REL and PRKCQ genes play in the pathology of autoimmune diseases, the association between polymorphisms in the REL and PRKCQ genes and BD was investigated." (PMID 26784953, 2016). "In the present study, the REL and PRCKQ genes were selected as candidates for the recently reported association of the REL and PRCKQ gene with other autoimmune diseases." (PMID 26784953, 2016). "Genome-wide association studies (GWAS) and candidate gene studies have identified the REL and PRKCQ genes as risk loci for various autoimmune diseases." (PMID 26784953, 2016).
lung carcinoma (8 papers, 2017 to 2024). "Survival analysis of lung cancer data in TCGA revealed that LUSC patients with high REL expression exhibited a significantly lower survival rate." (PMID 38495491, 2024). "In particular, overexpression of RELA is mainly found in ovarian cancer or cancer of the adrenal glands, whereas overexpression of c-REL is mainly found in lung cancer." (PMID 36879191, 2023). "For instance, RELA is most dominantly overexpressed in ovarian cancer and cancer of adrenal glands in comparison to RELB and c-REL, while the overexpression of c-REL is most abundantly found in lung cancers, compared to that of the other subunits." (PMID 29673141, 2018). "Accordingly, inhibition of MYC protein family members have been shown to induce regression of lung cancer in mice, suggesting the downregulation of MYC observed here likewise to be linked to the reduced proliferation of c-REL-/- cells." (PMID 28767691, 2017).
Sepsis (8 papers, 2013 to 2024). Sepsis is defined as life-threatening organ dysfunction caused by a dysregulated host response to infection. "Further studies are needed to investigate the functional role of this REL polymorphism on the inflammatory processes observed in sepsis and to validate these encouraging results in independent cohort." (PMID 27059500, 2016). "Functional data are needed to improve our understanding of how rs842647*G variant of REL is related to sepsis severity." (PMID 27059500, 2016). "We therefore speculate that excessive REL–mediated stimulation of Treg cells conferred by this mutation could lead to dysregulation of Treg-cell function in patients with sepsis and lead to organ dysfunction." (PMID 25880845, 2015). "As already mentioned, REL seems to be an interesting gene to study because NF-κB plays a central role in physiopathology of sepsis, and recent studies show the importance of cRel in this context." (PMID 27059500, 2016). "We then selected four SNPs (NFKB1 rs28362491 ins/delATTG, rs4648068 A/G, RELA rs7119750 C/T, and REL rs842647 G/A) from the canonical pathway of NF-κB and investigated their clinical relevance in relation to the development of sepsis and MODS." (PMID 25880845, 2015). "NF-κB transcription factor family members, including RELB, NFKB2, REL, and IRF1, predominantly control WARS1-induced gene expression networks, indicating recapitulating hyperinflammatory sepsis endotypes." (PMID 38177528, 2024).
colitis (7 papers, 2012 to 2022). Inflammation of the colon. "Given our observations and the association of REL polymorphisms with primary sclerosing cholangitis 29, a colitis‐associated cancer‐predisposing condition, this appears to be a pertinent question to address in the future." (PMID 25727407, 2015).
Cerebral ischemia (5 papers, 2015 to 2020). Restriction of arterial blood supply to the brain associated with insufficient oxygenation to support the metabolic requirements of the tissue. "Induction of anoxia both in vitro (via oxygen glucose deprivation of cortical neurons) and in vivo (using a model of cerebral ischemia) results in a reduction of nuclear RelA/c-REL and RelA/p50 dimers, whereas levels of p50/c-REL dimers remain unchanged." (PMID 28615451, 2017).
follicular lymphoma (5 papers, 2015 to 2022). Follicular lymphoma is a form of non-Hodgkin lymphoma characterized by a proliferation of B cells whose nodular structure of follicular architecture is preserved. "The second study reported the discovery of rearrangements or amplifications of the REL locus (encoding the NF-κB subunit c-REL) in two follicular lymphoma cases and one DLBCL." (PMID 36289712, 2022). "REL gains are also recurrent gene abnormalities in other hematopoietic cancers such as classical Hodgkin’s lymphoma, follicular lymphoma, MALT lymphoma, Burkitt’s lymphoma, and PMBL." (PMID 33959502, 2021). "Similarly, high REL levels have been shown to predict response to immunochemotherapy in follicular lymphoma." (PMID 32879628, 2020).
Stroke (5 papers, 2015 to 2023). Sudden impairment of blood flow to a part of the brain due to occlusion or rupture of an artery to the brain. "We summarize here how NPD1 elicits neuroprotection by up-regulating c-REL, a nuclear factor (NF)-κB subtype that, in turn, enhances expression of BIRC3 (baculoviral inhibitor of apoptosis repeat-containing protein 3) in the retina and in experimental stroke, leading to neuroprotection." (PMID 28615451, 2017).
chronic lymphocytic leukemia (4 papers, 2009 to 2019). "Except CCT4 gene which was also mapped to 2p as REL, these DEGs were not overlapping with those associated with 2p gain in chronic lymphocytic leukemia." (PMID 26324762, 2015).
atherosclerosis (3 papers, 2021 to 2025). A disease characterized by the build-up of fatty material and calcium deposition in the arterial wall resulting in partial or complete occlusion of the arterial lumen. "This underscores that inflammation and proliferation driven by endothelial c-REL contribute to early atherosclerosis." (PMID 39982773, 2025). "Our findings identify endothelial c-REL as a promising therapeutic target, offering a novel strategy to enhance EC function and alleviate atherosclerosis." (PMID 39982773, 2025). "We explored the effects of global suppression of c-REL on atherosclerosis using two approaches: constitutive c-Rel deletion and pharmacological inhibition using IT603." (PMID 39982773, 2025). "Here, we identify a role of endothelial c-REL in promoting inflammation and EC proliferation at sites of low shear stress and delineate the involvement of this pathway in atherosclerosis." (PMID 39982773, 2025). "In summary, we show that endothelial c-REL orchestrates the initiation of atherosclerosis at sites of disturbed flow by activating a TXNIP-p38 pathway leading to inflammation and a NF-κB2-p21 pathway driving proliferation." (PMID 39982773, 2025). "Inhibition of c-REL provides a novel therapeutic strategy to enhance EC function and reduce atherosclerosis." (PMID 39982773, 2025). "We hypothesized that c-REL may influence atherosclerosis given its pivotal role in regulating vascular inflammation." (PMID 39982773, 2025). "Therefore, to specifically dissect the influence of endothelial c-REL on atherosclerosis, we selectively deleted c-Rel from the endothelium using the Cdh5CreERT2/+ line crossed with a c-Relfl/fl mouse, generating c-RelECKO and control mice." (PMID 39982773, 2025). "Moreover, targeting c-REL may offer a dual benefit of protecting the vasculature and lowering plasma lipoprotein levels to attenuate atherosclerosis." (PMID 39982773, 2025).
colon cancer (3 papers, 2015 to 2021). "We also found REL-MNT co-IP in mouse Neuro-2a, human colon cancer LoVo, and rat glioma C6 cells (left)." (PMID 33419981, 2021). "Similarly, five genes including TOP2A, REL, SHH, ROS1, and CHEK2 in colon cancer gene network and three genes including RBL1, MAPK9, and PIK3CA in adenocarcinoma of lung gene network are selected." (PMID 29670664, 2018).
COVID-19 (3 papers, 2020 to 2024). A disease caused by infection with severe acute respiratory syndrome coronavirus 2. "Similarly in COVID-19, it can be expected that the activation of REL gene can lead to cytokine storm in the infected lung with SARS-CoV-2." (PMID 32754004, 2020). "Analysis of the transcription factors using the TRRUST database from our data (212 DEGs from GSE36854 and GSE21001) for MPXV infection and COVID-19 database by Metascape identified JUN, REL, STAT3, NFKB1, RELA, SP1, and so on." (PMID 37006463, 2023).
liver fibrosis (3 papers, 2016 to 2022). "The encoding protein of REL is the subunit of NF-κB, and the NF-κB signaling pathway has particular relevance to liver fibrosis." (PMID 35903097, 2022). "IRF8, NR4A2, IKZF3, and REL may be involved in the transcriptional regulation of NK cells in liver fibrosis." (PMID 35903097, 2022).
multiple sclerosis (3 papers, 2014 to 2020). A progressive autoimmune disorder affecting the central nervous system resulting in demyelination. "In summary, we present a human cellular model of neuronal differentiation exhibiting a novel essential function of NF-κB-c-REL in fate choice between neurogenesis and oligodendrogenesis which will potentially be relevant for multiple sclerosis and schizophrenia." (PMID 32331232, 2020).
Behçet disease (2 papers, 2016 to 2017). "The purpose of the present study was to investigate the association of the REL and PRKCQ genes with Behcet’s disease (BD) in a Chinese Han population." (PMID 26784953, 2016).
cervical cancer (2 papers, 2017 to 2022). A primary or metastatic malignant neoplasm involving the cervix. "Our findings emphasize the importance of c-REL signaling in a cellular model of cervical cancer with direct clinical implications concerning the resistance of cervical carcinoma to chemotherapeutic agents." (PMID 28767691, 2017). "In summary, our findings emphasize the importance of c-REL signaling in a cellular model of cervical cancer with direct clinical implications for the development of new treatment strategies." (PMID 28767691, 2017). "Our present findings for the first time transfer these promising data to the human cancerous systems and provide deeper insights into the biology of cervical cancers in relation to c-REL-signaling." (PMID 28767691, 2017). "In summary, our findings emphasize the importance of c-REL-signaling in a cellular model of cervical cancer particularly in terms of proliferation and resistance to chemotherapeutic agents." (PMID 28767691, 2017). "Here, we applied CRISPR/Cas9n-mediated genome editing to successfully knockout the NF-κB subunit c-REL in HeLa Kyoto cells as a model system for cervical cancers." (PMID 28767691, 2017). "To investigate the role of c-REL in human cervical cancers in more detail, we applied CRISPR/Cas9n-mediated genome editing in a multiplex way to delete c-REL in HeLa Kyoto cells." (PMID 28767691, 2017). "In the present study, knockout of c-REL in a cellular model of cervical carcinoma resulted in a significantly increased resistance against the chemotherapeutic agents 5-FUDR and cisplatin." (PMID 28767691, 2017). "While a knockout of c-REL promoted survival of HeLa cells to chemotherapy, expression of the c-REL homolog Xenopus Xrel3 in cervical cancer cells treated with 5 μM cisplatin was shown to result in increased apoptosis." (PMID 28767691, 2017).
combined immunodeficiency (2 papers, 2022 to 2025). A broad classification of inherited disorders presenting at birth that affect both the cell-mediated and humoral aspects of the immune response. "Finally, deficiency of c-REL in humans can be a cause for combined immunodeficiency (CID)." (PMID 36289712, 2022).
Hyperglycemia (2 papers, 2021 to 2023). An increased concentration of glucose in the blood. "In this study, hyperglycemia-induced cone-specific expression of NF-κB family members, including REL, RELA, and NFKB2." (PMID 34434927, 2021).
lymphoid tumors (2 papers, 2017 to 2022). "Whereas c-REL was currently discussed as being mutated in hematopoietic and lymphoid tumors, a high throughput database analysis performed in the present study including 3397 hematopoietic and lymphoid tumors detected mutations in only a few samples." (PMID 28767691, 2017).
squamous cell carcinoma (2 papers, 2013 to 2021). A carcinoma arising from squamous epithelial cells.
acute respiratory distress syndrome (1 paper, 2016). Progressive and life-threatening pulmonary distress in the absence of an underlying pulmonary condition, usually following major trauma or surgery. "In order to study the link between REL SNPs and septic shock severity, we compared acute respiratory distress syndrome (ARDS) and MODS frequencies, and VFD value between patients carrying REL rs842647*G and rs13031237*T minor alleles and in those homozygous for the major alleles." (PMID 27059500, 2016).
allergic dermatitis (1 paper, 2021). "The top differentially expressed genes (DEG) between AGS subjects and controls included transcription factors regulating immune gene expression, such as the NFκB pathway (NFKBIA, NFKB2, REL), antigen presentation molecules, type 2/allergic immune responses, itch, and allergic dermatitis." (PMID 33804792, 2021).
Ascites (1 paper, 2018). Accumulation of fluid in the peritoneal cavity (between the layers of the peritoneum that lines the abdomen). "Surprisingly, in the short-term ascites exposed population, REL and p65 were recruited to a similar extent at the −1,200 bp site of IL12B, while long-term exposure to ascites led to reduced but measurable recruitment." (PMID 29997615, 2018). "Since translocation of REL and p65 is impaired in the presence of ascites, and IL12B mRNA induction is prevented, while that of CXCL10 is not, an obvious hypothesis is that these transcripts are subject to gene-specific regulation." (PMID 29997615, 2018). "Because nuclear translocation of REL and p65 is diminished in the presence of ascites, we speculated that transcription of target genes other than IL12B may be affected." (PMID 29997615, 2018). "Unaltered occupancy of REL and p65 at both the IL12B and CXCL10 loci in the presence of ascites strongly suggests that these gene-specific mechanisms do not affect NFκB chromatin binding." (PMID 29997615, 2018).
cerebral edema (1 paper, 2021). "An important observation from our results is the overall higher expression of these transcriptional regulators, namely PPARG, REL, and NFE2L2 in PBMC at a delayed time point (>72 h), which falls within the time point of progressive cerebral edema after ICH." (PMID 33564466, 2021).
cerebral infarction (1 paper, 2022). An ischemic condition of the brain, producing a persistent focal neurological deficit in the area of distribution of the cerebral arteries. "In this study, REL and SOD2 were highly expressed in patients with cerebral infarction at the bulk RNA, single-cell RNA, and clinical levels." (PMID 35481271, 2022).
dental caries (1 paper, 2021). The decay of a tooth, in which it becomes softened, discolored, and/or porous. "Those genes; NFX1 and REL could contribute to dental caries by influencing host susceptibility to oral microorganism." (PMID 34311721, 2021).
glaucoma (1 paper, 2009). Increased pressure in the eyeball due to obstruction of the outflow of aqueous humor. "Alternatively, we performed immunohistochemical analysis of optic nerve slices from human donor tissue, which validated the activation of p50/NFKB1 and p65/c-REL subunits in glaucoma." (PMID 19426536, 2009).
microcephaly (1 paper, 2023). A congenital or acquired developmental disorder in which the circumference of the head is smaller than normal for the person's age and sex. "At this regard, it has been demonstrated in zebrafish embryos that the suppression of the expression of the ortholog of REL, a gene mapping between both main SROs, results in microcephaly." (PMID 36807877, 2023).
myeloid neoplasm (1 paper, 2023). Proliferation of myeloid cells originating from a primitive stem cell. "In conclusion, following an initial MRDneg-CR in AML or high-grade myeloid neoplasm, development of either REL-MRD or REL-MORPH were both associated with decreased OS." (PMID 37524920, 2023).
prostate (1 paper, 2022). "Studies have demonstrated that REL was expressed and localized in the epithelial or stromal cells after castrated prostate patients." (PMID 36324511, 2022).
retinoblastoma (1 paper, 2002). A malignant tumor that originates in the nuclear layer of the retina. "Twenty-five primary retinoblastoma tumours were analysed by real-time quantitative polymerase chain reaction to determine the genomic copy number of the N-MYC gene (2p24) relative to the copy number for REL, B2M, ALB, AF10 and MLL." (PMID 12232763, 2002).
Shock (1 paper, 2016). The state in which profound and widespread reduction of effective tissue perfusion leads first to reversible, and then if prolonged, to irreversible cellular injury. "We genotyped a population of 1040 ICU patients with septic shock and 855 ICU controls for two known polymorphisms of REL; REL rs842647 and REL rs13031237." (PMID 27059500, 2016).
vitiligo (1 paper, 2026). Generalized well circumscribed patches of leukoderma that are generally distributed over symmetric body locations and is due to autoimmune destruction of melanocytes. "The obtained findings suggest that IL2- and REL-related immune pathways influence vitiligo pathogenesis and clinical heterogeneity; however, these exploratory findings should be interpreted cautiously and require confirmation in studies with greater statistical power." (PMID 42278609, 2026).